MIR876 (microRNA 876)
Synonyms: hsa-mir-876; MIRN876; mir-876
Gene: MicroRNA gene on chromosome 9 (28,863,626 to 28,863,706, reverse strand). Ensembl gene ENSG00000215966.
Gene Ontology:
Biological process: miRNA-mediated post-transcriptional gene silencing
Cellular component: RISC complex
Homologues: Orthologues: chimpanzee ptr-mir-876 (100% identical), dog MIR876 (100% identical), macaque mml-mir-876 (100% identical), pig MIR876 (100% identical), guinea pig MIR876 (99% identical), rabbit MIR876 (96% identical), mouse Mir876 (89% identical).
Diseases named in the same sentence as MIR876 in open-access papers:
MIR876 is named in the same sentence as 1 disease in open-access papers, as found by Europe PMC text mining. Sharing a sentence is not in itself a finding about the gene and the disease. The quoted sentences say what the papers report.
melanoma (1 paper, 2024). A malignant, usually aggressive tumor composed of atypical, neoplastic melanocytes. "Analysis of the TCGA melanoma cohort indicated evidence of MIR876 copy number loss in a majority of melanoma samples." (PMID 39138582, 2024). "Subsequently, we assessed MIR876 copy number levels in the TCGA melanoma cohort and observed deletions in ~ 60% of cases." (PMID 39138582, 2024). "Analysis of the TCGA cohort revealed deletions in MIR876 in > 50% of melanomas." (PMID 39138582, 2024). "MIR876 copy number was determined in The Cancer Genome Atlas (TCGA) melanoma cohort." (PMID 39138582, 2024).